PCSK9 (proprotein convertase subtilisin/kexin type 9)
Diseases named in the same sentence as PCSK9 in open-access papers (continued):
Sharing a sentence is not in itself a finding about the gene and the disease.
nephrotic syndrome (13 papers, 2016 to 2025). A collection of symptoms that include severe edema, proteinuria, and hypoalbuminemia; it is indicative of renal dysfunction. "Preclinical studies indicate that elevated PCSK9 levels following podocyte injury contribute to lipid abnormalities in nephrotic syndrome, while PCSK9 deficiency ameliorates these changes." (PMID 40289090, 2025). "In contrast, total cholesterol or LDL-C levels showed no significant change in the statin-treated group, suggesting that PCSK9 inhibitors might be effective and safe alternatives for treating hypercholesterolemia associated with refractory nephrotic syndrome." (PMID 39148544, 2024). "As it was recently presented, up-regulation of PCSK9 gene expression could also be mediated by protein urinary loss in subjects with nephrotic syndrome or by protein peritoneal loss commonly observed in peritoneal dialysis patients." (PMID 26481479, 2016). "Plasma proprotein convertase subtilisin/kexin type 9 levels directly correlate to the amount of proteinuria in nephrotic syndrome patients." (PMID 36899379, 2023). "Here, for the first time, we report the successful use of the PCSK9 inhibitor in a patient with refractory nephrotic syndrome." (PMID 28683788, 2017). "We have described a case of refractory nephrotic syndrome successfully treated with a PCSK9 inhibitor." (PMID 28683788, 2017). "Recently, it has been shown that patients with nephrotic syndrome or patients with advanced renal failure treated by peritoneal dialysis displayed elevated plasma PCSK9 level." (PMID 26481479, 2016). "The exact mechanism of hypoalbuminemia–associated with elevated PCSK9 levels remains unknown but might be due to increased secretion of PCSK9 from hepatocytes coupled with decreased clearance encountered in nephrotic syndrome." (PMID 35354429, 2022). "Kyubok Jin reported that PCSK9 levels were higher in patients with nephrotic syndrome than in controls and that the elevated PCSK9 levels were associated with an increase in LDL cholesterol and TG, based on the examination of blood PCSK9 levels in those patients." (PMID 28683788, 2017). "Aggressive cholesterol-lowering abilities of PCSK9 inhibitors may be beneficial in patients with refractory nephrotic syndrome, so findings from similar cases are anticipated in the future." (PMID 28683788, 2017). "Furthermore, in rats with experimental nephrotic syndrome, an up-regulation of liver PCSK9 was observed." (PMID 26481479, 2016). "Therefore, PCSK9 inhibitors may be able to resolve lipid abnormalities in patients with nephrotic syndrome." (PMID 28683788, 2017). "Two previous reports in smaller groups (n = 15 Korean patients with nephrotic syndrome, i.e. proteinuria >3.5g/d, and n = 39 patients from the Netherlands with protein excretion of 1.9 [0.9–3.3] g/day) of patients with marked proteinuria observed rises in PCSK9." (PMID 26799206, 2016). "Studies also revealed that knockout mice with nephrotic syndrome lacking liver Pcsk9 exhibited a 40%–50% reduction in plasma cholesterol and triglycerides." (PMID 39148544, 2024). "However, it would be important to study if PCSK9 inhibitors can also alleviate proteinuria and CKD progression in patients with advanced CKD, such as nephrotic syndrome." (PMID 32733268, 2020).
peripheral artery disease (13 papers, 2016 to 2026). "Findings suggests that those with recent or multiple previous MIs, multivessel disease, multiple high-risk features, and peripheral arterial disease may be optimal candidates for PCSK9 inhibitors." (PMID 30895178, 2019). "Moreover, plasma PCSK9 levels are associated with CAD severity and the development of severe peripheral artery disease (PAD)." (PMID 36077166, 2022). "Moreover, plasma PCSK9 levels have been reported to be associated with the severity of CAD, and the presence of peripheral artery disease (PAD), especially those with extensive, severe, and complicated PAD." (PMID 29296222, 2017). "In addition, plasma PCSK9 levels were significantly higher in patients with peripheral artery disease, especially those with extensive, severe, and complicated forms of the condition, suggesting that PCSK9 functions as a proatherogenic molecule." (PMID 27658826, 2016). "In Greenlanders, rs12117661 also showed a non-significant association with a lower risk of peripheral artery disease, and in Europeans, it was very significantly associated with a lower risk of revascularization procedures and any CVD event, even when conditioning on the PCSK9 LoF variant." (PMID 37903942, 2024).
familial hypobetalipoproteinemia (12 papers, 2010 to 2026). "This is the first study conducted to investigate the genetic causes of hypobetalipoproteinemia in Lebanon, and to measure PCSK9 levels in familial hypobetalipoproteinemia caused by a missense mutation." (PMID 34564380, 2021). "Individuals with hypobetalipoproteinemia and PCSK9 mutation have inherited natural protection from CAD." (PMID 29850255, 2018). "A loss-of-function mutation in PCSK9 causes familial hypobetalipoproteinemia, which appears to lower risk for coronary artery disease and has no adverse sequelae." (PMID 25949827, 2015). "While this mutation causes a rare form of familial hypobetalipoproteinemia, the discovery of PCSK9 led to the successful development of a drug that may help prevent cardiovascular diseases." (PMID 37291571, 2023). "Some of them even had normal LDL-C levels, occasionally induced by a combination of a pathogenic and a favorable ‘counter’ mutation, causing hypobetalipoproteinemia, Proprotein convertase subtilisin/kexin type 9 (PCSK9) loss of function or hyperalphalipoproteinemia." (PMID 36752612, 2023). "In some cases, PCSK9 LOF mutations can lead to familial hypobetalipoproteinemia (FHBL)." (PMID 26586530, 2016). "Several mutations in the APOB, PCSK9, and MTP genes result in familial hypobetalipoproteinemia (FHBL) and abetalipoproteinemia (ABL) defined as low, or absent levels of apoB-100, and LDL-C in plasma." (PMID 26754661, 2016). "Whereas PCSK9 gain-of-function (GOF) mutations are associated with autosomal dominant hypercholesterolemia (ADH) and premature atherosclerosis, PCSK9 loss-of-function (LOF) mutations have a cardio-protective effect and in some cases can lead to familial hypobetalipoproteinemia (FHBL)." (PMID 26586530, 2016). "Several mutations in the ApoB, proprotein convertase subtilisin/kexin type 9 (PCSK9), and MTP genes result in low or absent levels of ApoB and LDL cholesterol in plasma, which cause familial hypobetalipoproteinemia and abetalipoproteinemia." (PMID 25949827, 2015). "The PCSK9 polymorphism found in patient AD3 was found to be present at a higher frequency in a low LDL-C population than in a normal population and to segregate with the "apoB- negative" Familial Hypobetalipoproteinemia phenotype in 3 families." (PMID 21235735, 2011).
liver fibrosis (12 papers, 2019 to 2025). "Genetic disruption and pharmacological inhibition of PCSK9 have been proven to decrease pulmonary fibrosis, liver fibrosis, and renal fibrosis, but the underlying mechanisms of the pro-fibrogenic effect have not been fully elucidated." (PMID 40076547, 2025). "Patients with the PCSK9 loss-of-function variant have shown higher protection against liver fibrosis." (PMID 40076547, 2025). "This research also described a protective role for the PCSK9 loss-of-function mutation against the progression of liver fibrosis." (PMID 39090671, 2024). "In summary, our study demonstrates that the expression of PCSK9 is closely associated with the level of hypoxia-induced autophagy during the development of CCl4-induced hepatic fibrosis." (PMID 37466835, 2023). "The association between PCSK9 and liver damage including liver fibrosis, in subjects with NAFLD or with liver cirrhosis has been explored recently." (PMID 34996457, 2022). "Therefore, prospective studies including participants of different races and populations and the underlying mechanisms of PCSK9 and liver fibrosis are required to validate the association between PCSK9 and liver fibrosis." (PMID 34996457, 2022). "In the tissues analysed herein 12 patients had cirrhosis and 20 patients had fibrosis stage 0, 1, 2 or 3, and therefore, the cohort may be better suited to identify associations of hepatic PCSK9 protein and stages of liver fibrosis." (PMID 33461570, 2021). "It should be noted that serum PCSK9 levels are also low in patients with advanced liver fibrosis, due to impaired PCSK9 release by the injured liver." (PMID 41271978, 2025). "A study by Stefania Grimaudo revealed that increasing PCSK9 expression in male mice led to faster progression of liver fibrosis." (PMID 39090671, 2024). "Given the central role of PCSK9 in mediating hypoxia-induced autophagy, we investigated its potential impact on CCl4-induced liver fibrosis in the mice." (PMID 37466835, 2023). "Evaluated via immunohistochemistry (IHC), the expression of PCSK9 increased gradually with the aggravation of liver fibrosis, concentrated mainly around the fibrotic areas." (PMID 37466835, 2023). "With the evidence that PCSK9 expression increased during liver fibrosis, we examined the effect of hypoxia on PCSK9 expression in hepatocytes." (PMID 37466835, 2023). "In the current study, of note were the increase of PCSK9 that paralleled autophagy in the hepatocytes, and the inhibition of PCSK9 that decreased autophagy and alleviated liver fibrosis, which was different from any previously reported evidence." (PMID 37466835, 2023). "In the current study, we discovered the effect of anti-PCSK9 therapy on liver fibrosis when the hypoxia-induced autophagy was inhibited in hepatocytes." (PMID 37466835, 2023). "Overall, the findings indicated that anti-PCSK9 treatment improved liver fibrosis by regulating hypoxia-induced autophagy in hepatocytes through the AMPK/mTOR/ULK1 signaling pathway." (PMID 37466835, 2023). "The results showed that PCSK9 expression was upregulated with the development of liver fibrosis, which was accompanied by enhanced autophagy." (PMID 37466835, 2023). "This study aimed to investigate the mechanism of anti-PCSK9 treatment on liver fibrosis by inhibiting hypoxia-induced autophagy." (PMID 37466835, 2023). "In our previous study, similarly, PCSK9 inhibition was observed to reduce intestinal endotoxemia, thereby attenuating liver fibrosis." (PMID 37466835, 2023). "Anti-PCSK9 treatment alleviates liver fibrosis by regulating hypoxia-induced autophagy in the hepatocytes through AMPK/mTOR/ULK1 signaling pathway." (PMID 37466835, 2023). "In the current study, we used a CCl4-induced model of canonical liver fibrosis mice to get a deep insight into the mechanism, with the application of both exogenous PCSK9 inhibition with PCSK9 mAb Evolocumab and endogenous PCSK9 inhibition by CRISPR-Cas9 AAV." (PMID 37466835, 2023).
liver fibrosis (continued). "Our previously reported study found that PCSK9 expression increased in liver fibrosis and that anti-PCSK9 treatment alleviated liver injury." (PMID 37466835, 2023). "We further examined the effect of PCSK9 inhibitor on alcohol-induced liver injuries by assessing liver fibrosis." (PMID 31748600, 2019). "The serum level of PCSK9 is positively correlated with liver fibrosis." (PMID 40076547, 2025). "Subsequent research has indicated that anti-PCSK9 treatment may hold the potential to mitigate liver fibrosis by modulating the AMPK/mTOR/ULK1 signaling pathway, thus reducing hypoxia-induced autophagy in hepatocytes." (PMID 39090671, 2024). "Admittedly, liver fibrosis is accompanied by increased inflammation; therefore, we investigated whether inflammation could affect the expression of PCSK9 in hepatocytes." (PMID 37466835, 2023). "Thus, PCSK9 has promising potential of becoming a new biomarker as a therapeutic target for the treatment of hepatic fibrosis." (PMID 37466835, 2023). "To elucidate the mechanism of PCSK9 regulating hypoxia-induced autophagy in liver fibrosis, we performed transcriptome sequencing of the liver tissues from CCl4-treated and CCl4 + AAV8-sgPCSK9 mice, as indicated by the heat map and volcano map of differential genes." (PMID 37466835, 2023). "PCSK9 is highly expressed in the liver, and stage of liver fibrosis may be a confounding factor influencing PCSK9 levels." (PMID 35162992, 2022). "Whether liver damage, especially liver fibrosis, has an impact on the predictive ability of PCSK9 for adverse cardiovascular outcomes is worth exploring." (PMID 34996457, 2022). "Furthermore, the effect of the combination of PCSK9 and noninvasive liver fibrosis scoring systems on cardiovascular risks lacks evidence." (PMID 34996457, 2022). "One can speculate that decreased levels of circulating PCSK9 in liver fibrosis could be due to dysfunctional PCSK9 synthesis in hepatocytes of the damaged liver." (PMID 35162992, 2022). "Identification of the underlying mechanisms is essential to clarify whether blockage of PCSK9 may be a suitable approach to reduce LDL levels in patients with severe liver fibrosis." (PMID 33461570, 2021). "Therefore, the evidence indicated that PCSK9 expression and autophagic activity increased in parallel with the progression of liver fibrosis; hence, there may be a functional interaction between PCSK9 and autophagy in CCl4-induced liver fibrosis." (PMID 37466835, 2023). "This study provided new insights into the relationships among PCSK9, liver fibrosis, and cardiovascular risks in patients suspected of having CAD, further raising the question of whether PCSK9 inhibitors may have considerable cardiovascular benefits in patients with liver fibrosis." (PMID 34996457, 2022). "Western blot also showed that YC-1 significantly decreased the expression of PCSK9, LC3B-II, and BECN1, respectively, and increased the expression of p62 during liver fibrosis." (PMID 37466835, 2023). "Carbon tetrachloride-induced mouse liver fibrosis and mouse hepatocyte line AML12, cultured under the hypoxic condition, were established to undergo PCSK9 inhibition." (PMID 37466835, 2023). "Oncostatin M is an effective inducer of liver fibrosis and was shown to increase LDL-R levels in cells and hypercholesterolemic rabbits, possibly via inhibition of PCSK9." (PMID 35162992, 2022). "Thus, we postulates that the inhibition of PCSK9 by alirocumab, a monoclonal antibody against PCSK9, can decrease ox-LDL level, attenuate liver fibrosis, and intrahepatic inflammation; then, it consequently ameliorates cirrhosis-related complications." (PMID 35806383, 2022). "In view of which, we are not in a position to know whether anti-PCSK9 treatment can improve liver fibrosis." (PMID 37466835, 2023).
liver fibrosis (continued). "HIF-1α is a critical regulator of cellular and systemic responses to low oxygen levels, and hepatocyte hypoxia contributes directly to the progression of liver fibrosis; therefore, we hypothesized that HIF-1α could play an important role in PCSK9 expression and autophagy during liver fibrosis." (PMID 37466835, 2023). "The APASHA model—consisting of APOF, PCSK9, AFM, S100A6, HbA1c %, and AZGP1—showed an excellent discriminatory capacity with an AUROC of 0.8875 (CI 0.82–0.96) to discriminate MASH, but not liver fibrosis." (PMID 40250425, 2025).
myocardial ischemia (12 papers, 2020 to 2025). A disorder of cardiac function caused by insufficient blood flow to the muscle tissue of the heart. "PCSK9 inhibitor pretreatment has also been shown to prevent brain injury caused by myocardial ischemia/reperfusion damage by reducing dendritic spine loss, attenuating microglial overactivation, and inhibiting Aβ aggregation." (PMID 39157774, 2024). "In a myocardial ischemia–reperfusion (I/R) model in Wistar rats, a PCSK9 inhibitor administered before ischemia exerted a cardioprotection, as demonstrated by the attenuation of infarct size and cardiac arrhythmia during cardiac I/R injury." (PMID 39982361, 2025). "The release of PCSK9 during cardiac ischemia results in cell death and dysfunction; inflammatory stimuli (i.e., IL-1β) are considered to be powerful inducers for PCSK9 secretion in both macrophages and tissues such as heart and aorta." (PMID 34576046, 2021). "So far an increased expression of PCSK9 in mice hearts, which have been subjected to acute ischemia/reperfusion (present study), myocardial ischemia for 1 week, as well as in human hearts with recent infarcts, was found." (PMID 33169229, 2020). "Furthermore, recent studies have shown that pretreatment with PCSK9 inhibitor (PCSK9i), at the time of preischemic myocardial ischemia, can play a critical role in prevention of this disease." (PMID 38887452, 2024). "PCSK9 inhibition with the PCSK9 inhibitor (PCSK9i) Prep2-8 trifluoroacetate salt significantly reduced levels of Phospho-NFκB/ NFκB and reactive microglia and astrocytic proliferation and hypertrophy in a rat model of cardiac ischemia/reperfusion injury." (PMID 33919550, 2021). "In addition, hearts isolated from PCSK9 knockout mice showed increased postischemic left venctricular function and therefore an improved recovery after suffering from myocardial ischemia." (PMID 33169229, 2020).
systemic lupus erythematosus (12 papers, 2020 to 2025). An autoimmune multi-organ disease typically associated with vasculopathy and autoantibody production. "For instance, serum PCSK9 level is increased in systemic lupus erythematosus (SLE) patients compared to HCs, and it is positively related to disease activity and inflammatory markers in SLE patients." (PMID 37249282, 2023). "Earlier, we have reported that PCSK9-levels are raised among patients with high disease activity in systemic lupus erythematosus (SLE) and that OxLDL induced PCSK9 in dendritic cells (DC), effects which were significantly stronger in DCs from SLE patients than from controls." (PMID 33461620, 2021). "In a pristane‐induced systemic lupus erythematosus (SLE) mouse model, pharmacological inhibition of PCSK9 significantly attenuated systemic inflammation, as evidenced by a 40–50% reduction in proinflammatory cytokines (IL‐17, TNF‐α) and increase in anti‐inflammatory TGF‐β levels (p < 0.01)." (PMID 41190281, 2025). "In addition, we also found that FNLS-YE1 could efficiently introduce protective alleles in TYK2 /WDFY4 and PCSK9/ANGPTL4, offering a potential approach to reduce susceptivity for systemic lupus erythematosus (SLE) and familial hypercholesterolemia (FH), respectively." (PMID 37285261, 2023).